INS (insulin)
Diseases named in the same sentence as INS in open-access papers (continued):
Sharing a sentence is not in itself a finding about the gene and the disease.
diabetes (continued). "This evidence further supports HBOT-induced increased insulin sensitivity as the proposed mechanism for reducing blood glucose levels in patients with type 2 diabetes mellitus." (PMID 34684171, 2021). "The standard drug glibenclamide helps in diabetes management by controlling insulin secretion and insulin action." (PMID 34925813, 2021). "More and more research is focusing on the role IDE (insulin-degrading enzyme) in modulate insulin level, arising amyloid β (Aβ) and development of cognitive impairment characteristic for the type 2 diabetes mellitus (T2DM) and Alzheimer’s disease." (PMID 33918576, 2021). "T2DM is a form of diabetes mainly characterized by high blood glucose, insulin resistance, and relatively a weaker insulin-stimulated response under hyperglycemic conditions." (PMID 34831299, 2021). "It is, therefore, unfortunate that many Medicare beneficiaries with insulin-treated diabetes who would benefit from insulin pump use are denied access to this technology because of onerous, medically unfounded eligibility criteria." (PMID 34077674, 2021). "International guidelines report sulphonylureas as the first-line treatment for monogenic diabetes, so we decided to start therapy with gliclazide RM (60 mg) suspending insulin at all (Visit 2)." (PMID 34654408, 2021). "Having said this, there are hardship funds available among some hospitals in Bangladesh to help cover the costs of insulin for the very poor given concerns with the potential catastrophic impact on the family if members have diabetes." (PMID 34249838, 2021). "China has become and will continue to be a country burdened with huge diabetes, which requires our government and society to pay more attention to the access to insulin, the life-saving medicine." (PMID 34383816, 2021). "Insulin degludec (IDeg) is one of several second-generation long-acting insulin analogs approved in the USA to improve glycemic control in patients with diabetes mellitus, available in the USA as of January 2016." (PMID 33550540, 2021). "Patient 1 suffered from very severe diabetes with persistent glycemic imbalance despite very high insulin doses." (PMID 34342583, 2021). "Taken together, these results suggest that short-term CR in the late stage of diabetes, with decreases in blood insulin levels, can help to maintain blood insulin levels, potentially by reducing IDE levels." (PMID 33916828, 2021). "Ginsenosides not only improve glucose metabolism, increase insulin sensitivity, and promote lipid transport, but also alleviate symptoms of obesity-related complications like diabetes and NAFLD." (PMID 34512356, 2021). "It is known that endoplasmic reticulum stress (ERS) activation is a strong molecular link between obesity, lipodystrophy, functional insulin damage, and the development of type 2 diabetes mellitus." (PMID 33807589, 2021). "In a large longitudinal study of 1441 people with T1D in the Diabetes Control and Complications trial (DCCT), intensive insulin treatment reduced the risk of developing DPN by 60%." (PMID 33498918, 2021). "Diabetes is characterized by chronic hyperglycemia with impaired carbohydrate, fat, or protein metabolism due to impaired insulin secretion, insulin resistance, or both." (PMID 34207217, 2021). "The relevance between diabetes and β-cell dysfunction is a fundamental research topic for the development of new therapies increasing insulin secretion and optimizing metabolism of T1DM." (PMID 34262457, 2021). "As MILES is a prospective study, in the future we will be able to assess the predictive value of the components of insulin homeostasis on incident diabetes." (PMID 34206745, 2021). "Diabetes increases oxidative stress, which in turn can worsen both insulin action and secretion, thereby accelerating the progression to overt the disease." (PMID 34439554, 2021).
diabetes (continued). "Overall, the evidence suggest that exercise interventions appear superior to nutrition alone in improving CRF and reversing progress to diabetes by improving insulin sensitivity among children and adolescents with overweight/obesity." (PMID 33669882, 2021). "Strengthening the importance of independence in the treatment of diabetes, one study emphasized that patient-managed dosage titration for simple bolus insulin is as effective as physician-driven dosage adjustment." (PMID 35047273, 2021). "Insulin was discovered exactly 100 years ago due to its ability to lower blood glucose in patients with diabetes." (PMID 34440929, 2021). "It raises urgent needs to identify new molecules that enhance insulin signaling or can be used as insulin replacement for treating diabetes." (PMID 34489478, 2021). "LATS2 deficiency in β-cells and primary isolated human islets as well as β-cell specific LATS2 ablation in mice improves β-cell viability, insulin secretion and β-cell mass and ameliorates diabetes development." (PMID 34389720, 2021). "Recently, the incretin effect has been observed to be reduced in patients with type 2 diabetes mellitus, which is a symptom of increased insulin secretion induced by oral administration, such as eating a meal, compared to intravenous administration of glucose." (PMID 34451706, 2021). "Diabetes is the result of a cluster of metabolic alterations including insulin resistance, lower insulin secretion, or increased glucagon secretion leading to hyperglycemia." (PMID 33467677, 2021). "Diabetes mellitus (DM) and obesity are considered metabolic-disorder-related diseases, and DM is characterized by hyperglycemia resulting from defects in insulin secretion, insulin action, or both." (PMID 33927693, 2021). "It is also possible that the opening of the territory’s first endocrinology-diabetes-nutrition specialty service in April 2017 has promoted patient autonomy and limited the use of insulin." (PMID 34917037, 2021). "Among the 225 cancer survivors with diabetes, 179 (80%) reported taking anti-glycemic medication or insulin at baseline." (PMID 32901370, 2021). "Quality of life has been shown to be significantly impaired in CF-related diabetes, especially when requiring insulin." (PMID 34404378, 2021). "Rin-5f cell lines are insulin-secreting pancreatic cancer cells and are used to confirm various insulin- and diabetes-related mechanisms." (PMID 33435282, 2021). "In this study, occurrence of macro‐ and microvascular complications was higher in insulin‐treated participants compared with insulin‐naïve participants, possibly owing to the shorter duration of diabetes in the latter." (PMID 34277959, 2021). "Ninteen studies were conducted with diabetes-induced SD rats, and most of the extracts showed effectiveness in regulating insulin secretion or resistance." (PMID 33435282, 2021). "Dietary fibre can reduce blood glucose and insulin levels in people with diabetes by consuming grain foods, vegetables and fruits." (PMID 34360317, 2021). "Diabetes mellitus (DM) is a metabolic disease characterized by chronic hyperglycemia resulting from dysfunctional insulin secretion or insulin action." (PMID 33859349, 2021). "And GLP-1 plays an important role in promoting insulin secretion, inhibiting glucagon secretion and stimulating the proliferation and differentiation of islet beta cell in patients with diabetes." (PMID 34001220, 2021). "Patients with diabetes have lower circulating levels of vitamin C and higher level of lipid peroxides, reports also suggest improvement in insulin action, glycemic control and endothelial function." (PMID 33653396, 2021). "An important observation was lower insulin secretion in patients from northern Ukraine with new-onset adult diabetes compared to the Swedish ANDIS cohort." (PMID 34276762, 2021).
diabetes (continued). "In hepatogenous diabetes, the specific pathophysiological pathways include impaired insulin sensitivity, which represents an early event, and subsequently beta-cell dysfunction, essential for the transition to frank diabetes." (PMID 33800465, 2021). "Ketogenic diets were the treatment of choice for diabetes prior to the discovery of insulin in the early 1920s." (PMID 34684300, 2021). "For instance, insulin action in AgRP neurons is required to efficiently suppress hepatic glucose production, and abrogation of insulin and leptin receptors from POMC neurons causes diabetes in mice." (PMID 34002087, 2021). "Diabetes is determined by high levels of blood glucose due to defects of insulin production and action, or both." (PMID 33809267, 2021). "Some evidence indicates that insulin treatment in patients with diabetes can affect the coagulatory system." (PMID 34283877, 2021). "Iron accumulation in islets is consistent with human HH, which is typified by the development of diabetes (due to oxidative damage to insulin-producing β cells)." (PMID 34143808, 2021). "It would be overly simplistic to only recognize hyperglycemia as the culprit in diabetes, but insulin resistance also induces signaling pathways which are involved in the micro and macro vascular pathologies which are seen in diabetes." (PMID 33708143, 2021). "Insulin secretion decreased mainly between prediabetes and diabetes, whereas insulin clearance was reduced in prediabetes compared to normal glucose tolerance." (PMID 34206745, 2021). "In diabetes, oxidative stress interrupts glucose metabolism’s normal coupling to insulin secretion by activating stress signaling nuclear factor-κB (NF-κB) and p38 mitogen-activated protein kinase (MAPK) pathways." (PMID 33435215, 2021). "Using a relatively recently available ultrasensitive C-peptide assay in a cross-sectional study we demonstrated insulin microsecretion (detectable C-peptide levels) in 55.3% of people with diabetes, including 64.1% of adults and 34.0% of youth with diabetes." (PMID 34083567, 2021). "Among the patients with diabetes who routinely self-administer subcutaneous insulin injections, the rates of pre-injection skin disinfection are 16% in Spain and 30.0% in Italy." (PMID 33916158, 2021). "The rs4684847 risk allele, by binding the homeobox transcription factor PRRX1, represses PPARG2, perturbs lipid metabolism and insulin sensitivity, and contributes to the onset of diabetes." (PMID 33919522, 2021). "We report a case of a 40-year-old African male with a history of diabetes mellitus with multiple microvascular complications, having recently initiated insulin treatment with a rapid decline in glycosylated hemoglobin (HbA1c) concentration." (PMID 34540416, 2021). "The DIGAMI trial is a prospective randomized control trial involving coronary care units of 19 Swedish hospitals, that first established a mortality benefit of intensive blood glucose control with insulin on the outcome of patients with diabetes suffering AMI." (PMID 33463901, 2021). "A century ago, insulin was purified from canine pancreata and administered to people with diabetes mellitus." (PMID 34841432, 2021). "Studies have found that individuals with pre-diabetes or diabetes who received an earlier LCHF diet revealed several beneficial outcomes, including weight loss, improved insulin sensitivity, glucose homeostasis, and lower fasting blood glucose levels." (PMID 34795641, 2021). "Because of this, we examined the association between serum PRSS8 levels and existence of type 2 diabetes mellitus (T2DM) patients, biomarkers of arteriosclerosis, and insulin secretion in human individuals." (PMID 34361079, 2021). "In experimental diabetes, muscles with a predominantly slow-twitch fiber profile exhibit greater insulin sensitivity and greater glucose uptake than muscles with a predominantly fast-twitch fiber profile." (PMID 34671252, 2021).
diabetes (continued). "Hepatic insulin resistance is defined as the impaired ability of hepatocytes to respond to insulin, which contributes to the progression of type 2 diabetes mellitus (T2DM) and metabolic syndrome." (PMID 34140896, 2021). "A study that studies the effects of HT and DHPG on the evolution of diabetes is desirable, but perhaps that should be studied in an experimental model of type 2 diabetes, where tissue mechanisms (insulin resistance) are more important." (PMID 34943086, 2021). "The use of a microbiome-dependent transgenic mouse model of diabetes would be useful to test the effects of inter-ethnic differences in the microbiome on insulin and glucose tolerance." (PMID 34617511, 2021). "We revealed that in multivariate regression models for almost all NCS parameters, beside height and diabetes duration, significant factors were basal insulin dose per kilogram of weight (BID/kg), body mass index (BMI), and thyroid hormones." (PMID 34822453, 2021). "Patients with type 1 diabetes mellitus (T1DM) rely on exogenous insulin for blood control and survival." (PMID 34489478, 2021). "Type 1 diabetes mellitus is considered an autoimmune disease, in which T-cells mediate the elimination of pancreatic β-cells and thereby contribute to the production of low insulin levels." (PMID 36699147, 2021). "The purpose of the current study is to evaluate if a patient family history of diabetes is related to the efficiency of lifestyle intervention on insulin resistance and insulin secretion in a cohort of metabolic syndrome with 2-year follow-up." (PMID 33490287, 2021). "Fragility fractures are now recognized as an important complication of both diabetes mellitus type 1 and type 2, particularly in those with long-term disease, poor glycaemic control, β cells failure and insulin treatment." (PMID 34445256, 2021). "Because insulin facilitates the uptake of sugar into cells from the bloodstream, diabetes results in elevated levels of blood glucose." (PMID 34661545, 2021). "Diabetes duration of seven years or more was found in 38.1% of subjects; 25.9% used oral hypoglycemic agents or insulin injection treatment and 2.5% used diet or exercise therapy as non-drug treatments." (PMID 33915834, 2021). "Notable, not only improvement in insulin sensitivity is of importance for the remission of diabetes after RYGB, another important denominator for remission is the insulin secretory capacity of the pancreatic beta‐cells." (PMID 33463892, 2021). "In T2DM (hereafter referred to as diabetes), a condition that corresponds to ~90–95% of all diabetes cases, cells become resistant to insulin, leading to the dysregulation of glucose metabolization." (PMID 34574099, 2021). "The diabetes field is particularly dedicated to understanding motivation of insulin self‐management, or lack thereof, using person‐reported outcome measures to focus encounters on life domains important to the patient." (PMID 34414588, 2021). "In humans, we found that the expression of IRF3 in WAT is positively correlated with peripheral insulin sensitivity and is negatively correlated with severity of diabetes." (PMID 34091599, 2021). "We classified 495 diabetic lung adenocarcinoma patients according to the diabetes medication used, such as metformin, insulin, or others (including acarbose, SU, and TZD)." (PMID 34439918, 2021). "We propose that measuring HbA1c and insulin should also be included to detect any glucose metabolism dysregulation (e.g., diabetes, prediabetes, hyperglycemia, IGT, IFG, hyperinsulinemia)." (PMID 34395368, 2021). "The use of EMR offers the opportunity to transfer data of diabetes technology, such as glucose monitoring systems, insulin pumps, or insulin pens, directly to the patients’ medical records." (PMID 33759789, 2021). "Liver-specific deletion or pharmacological blockade of the GR has been shown to have beneficial effects, including decreased fasting plasma glucose and insulin levels and reducing the progression to diabetes." (PMID 33435513, 2021).
diabetes (continued). "Type 2 diabetes mellitus (T2DM) is the most widespread form of diabetes, characterized by chronic hyperglycaemia, insulin resistance, and inefficient insulin secretion and action." (PMID 34451903, 2021). "Anthocyanins, like cyanidin and delphinidin 3-glucoside, have shown to improve insulin resistance, insulin production, and hepatic glucose uptake during type 2 diabetes mellitus." (PMID 34209338, 2021). "The relation between glucose uptake in AT with obesity, insulin sensitivity and diabetes was already demonstrated before." (PMID 32886301, 2021). "Diabetes mellitus (DM) is defined as a group of metabolic pathologies characterized by compromised insulin production and/or function, leading to hyperglycemia." (PMID 32244718, 2020). "In vivo studies have shown that kaempferol down-regulated IKK and suppressed NF-kappa B pathway activation to reduce hepatic inflammatory lesions, which was helpful to insulin signaling defect in diabetes." (PMID 33292335, 2020). "The small number of participants in the diabetes group, and particularly the insulin restriction subgroup, is a limitation of the study." (PMID 32128205, 2020). "Diabetes mellitus (DM) is a disorder of carbohydrate, fat and protein metabolism attributed to low production of insulin or mounting resistance to its action leading to persistent hyperglycemia." (PMID 33335883, 2020). "No hypoglycemia was documented at 02h00 and the median glucose values for the total cohort and diabetes subtypes at this time point, argue that a conservative increase in basal insulin during the first 48 h, usually administered at bedtime, will be safe." (PMID 33519707, 2020). "Amongst all other diabetes treatments, one that stands out as requiring special attention, due to it repelling a number of patients, is insulin." (PMID 33193981, 2020). "Glycated hemoglobin reduced considerably when HCQ was combined with insulin for the treatment of diabetes mellitus, compared with patients receiving placebo, and the insulin dose had to be lowered by 30% in the HCQ group." (PMID 33062720, 2020). "Diabetes can be type 1 diabetes with an insufficient insulin level or it can be type 2 diabetes where tissues have insensitivity to insulin (insulin resistance)." (PMID 32397116, 2020). "There has been some concern over: the use of some glucose lowering medications in the older population with diabetes, particularly sulfonylureas and insulin; and in setting appropriate levels for glycemic control." (PMID 32256448, 2020). "Hypoglycemia is a common side effect of insulin therapy in diabetes, and it is one of the important limiting factors in the glycemic management of patients with diabetes." (PMID 33204733, 2020). "The results suggest the significant influence of extract on diabetes levels that was significantly decreased in terms of blood glucose and insulin levels." (PMID 32971839, 2020). "Elevated insulin level in diabetes promotes Aβ accumulation by competing with Aβ for insulin-decomposing enzyme." (PMID 33076507, 2020). "Currently, the demand of insulin is increasing due to the high levels of diabetes (type 1 and type 2) within the general population." (PMID 33816979, 2020). "Diabetes mellitus (DM) is a chronic metabolic disorder represented by hyperglycemia, resulting from insufficient insulin secretion or its ineffective action with variations in carbohydrate, lipid, and protein metabolism." (PMID 32143382, 2020). "Diabetes mellitus is a chronic metabolic disorder, primarily characterized by hyperglycemia arising from insulin insensitivity, damaged secretion of insulin, and inflammatory response." (PMID 32520209, 2020). "As we briefly summarised above, in recent years our understanding of post-transcriptional and translational mechanisms for insulin production and their impairment in diabetes has progressed relentlessly." (PMID 32894308, 2020).